HOXA9 (homeobox A9)
Diseases named in the same sentence as HOXA9 in open-access papers (continued):
Sharing a sentence is not in itself a finding about the gene and the disease.
osteosarcoma (12 papers, 2020 to 2024). A usually aggressive malignant bone-forming mesenchymal neoplasm, predominantly affecting adolescents and young adults. "Silencing of miR-641 promoted osteosarcoma cell proliferation and metastasis by targeting homeobox protein Hox-A9 (HOXA9)." (PMID 35069784, 2022). "Reverse transcription-polymerase chain reaction (RT-PCR) was used to detect the expression of miR-652 and HOXA9 in osteosarcoma tissues and normal tissues." (PMID 35111226, 2022). "It was reported that overexpression of HOXA9 promotes the ability of proliferation, invasion, and migration in osteosarcoma cells through upregulating the protein expression of p-PI3K, p-Akt, MMP2, and MMP9." (PMID 36376832, 2022). "The results of the RT-qPCR assay showed that miR-652 was significantly downregulated in osteosarcoma tissues, and then the target gene interacting with miR-652 was predicted by bioinformatics to be HOXA9." (PMID 35111226, 2022). "Several studies have found that lncRNAs play an important role in tumor progression, such as the down-regulation of linc01140, which inhibits proliferation and the invasion of osteosarcoma by targeting the miR-139-5p/HOXA9 axis." (PMID 36135086, 2022). "The expression of miR-652 is low in osteosarcoma, and miR-652 inhibits the viability and migration of osteosarcoma cells by regulating HOXA9." (PMID 35111226, 2022). "At the same time, the regulatory effect of miR-652 on HOXA9 was analyzed in order to provide a new idea for gene-targeted therapy of osteosarcoma." (PMID 35111226, 2022). "It is inferred that miR-652 regulates the proliferation, migration, and invasion of osteosarcoma cells by targeting HOXA9." (PMID 35111226, 2022). "The miR-652 overexpression models were established by transfecting miR-652 mimics into osteosarcoma U-2OS cells, and HOXA9 overexpression models were simultaneously established by transfecting pcDNA3.1-HOXA9 into osteosarcoma U-2OS cells." (PMID 35111226, 2022). "For instance, miR-196 inhibits the expression of Hoxb8, resulting in downregulation of Shh expression in mouse forelimb development, whereas its overexpression suppresses cell proliferation and migration by suppressing HOXA9 in human osteosarcoma cell lines." (PMID 33572377, 2021). "Interestingly, it is known miR-1294 targets HOXA9 and has a tumor suppressive role in osteosarcoma where it is down-regulated, correlating with a poor 5 year overall survival." (PMID 38203740, 2024). "Furthermore, LINC01140 and LncRNA DLX6-AS1 were reported to regulate the malignant behaviors including proliferation, invasion, and metastasis in Osteosarcoma through targeting HOXA9." (PMID 36376832, 2022). "miR-652 and HOXA9 showed low expression and overexpression, respectively, in osteosarcoma tissues." (PMID 35111226, 2022). "The results of the RT-qPCR assay showed that the mRNA expression level of HOXA9 in osteosarcoma tissues was significantly higher than that of normal tissue, and the mRNA expression level of HOXA9 in osteosarcoma cell lines was significantly higher than that of normal osteoblasts." (PMID 35111226, 2022). "Research reported that HOXA9 was identified as a downstream target of miR-1294 in osteosarcoma." (PMID 36376832, 2022). "miR-652 may negatively regulate HOXA9 expression and inhibit the proliferation, migration, and invasion abilities of osteosarcoma cells through the PI3K/Akt signaling pathway." (PMID 35111226, 2022). "Furthermore, HOXA9 as a direct target of miR-429, miR-873, miR-652, miR-182, miR-641, and miR-139-5p were also verified by luciferase reporter assay in osteosarcoma." (PMID 36376832, 2022). "In addition, we observed that study about HOXA9 as a target of these miRNAs in osteosarcoma is more than in other solid tumors, prompting that HOXA9 might implement a crucial role in osteosarcoma regulated by miRNAs." (PMID 36376832, 2022).
osteosarcoma (continued). "Proliferation, invasion, and migration abilities of osteosarcoma cells and the level of protein expression of p-PI3K, p-Akt, MMP2, and MMP9 were significantly decreased with enhanced miR-652 expression (P < 0.01), while overexpression of HOXA9 reversed this situation." (PMID 35111226, 2022). "However, the specific role and mechanism of HOXA9 in osteosarcoma is not clear." (PMID 35111226, 2022).
bladder cancer (11 papers, 2011 to 2024). "Our results show that HOXA9 promoter methylation status is associated with response to cisplatin-based chemotherapy in bladder cancer cell lines and in metastatic bladder cancer." (PMID 27598218, 2016). "In bladder cancer, promoter methylation of HOXA9 has been associated with detection, aggressiveness and prognostication." (PMID 27598218, 2016). "Methylation levels of EOMES, HOXA9, POU4F2, TWIST1, VIM, and ZNF154 in urine specimens are promising diagnostic biomarkers for bladder cancer recurrence surveillance." (PMID 23056278, 2012). "Reinert and collaborators established a detailed mapping of the methylome in bladder cancer and identified four novel DNA methylation marks: HOXA9, ZNF154, POU4F2, and EOMES." (PMID 22829811, 2012). "Decitabine treatment reversed cisplatin resistance in bladder cancer cells, and it was therefore suggested that HOXA9 could predict response to cisplatin-based chemotherapy in patients with bladder cancer." (PMID 38256203, 2024). "In the present study, we found in a translational stepwise approach that promoter DNA methylation of the homeobox (HOX) gene HOXA9 could help predict resistance or response to cisplatin-based chemotherapy in patients with bladder cancer." (PMID 27598218, 2016). "HOXA9 methylation has been proposed as a urinary biomarker for bladder cancer diagnosis." (PMID 27598218, 2016). "The methylation status of a 4-gene panel (HOXA9, EOMES, POU4F2, and ZNF154) was significantly different between urine samples from bladder cancer patients and healthy individuals." (PMID 37627900, 2023). "In urine samples, the methylation status of a urinary biomarker panel (HOXA9, ONECUT2, PCDH17, PENK, TWIST1, VIM, and ZNF154) showed great prediction accuracy in predicting bladder cancer in patients with hematuria." (PMID 37627900, 2023). "In another study, the correlation between the methylation levels of EOMES, HOXA9, POU4F2, TWIST1, VIM, and ZNF154 in urine specimens and bladder cancer recurrence surveillance was discovered by real-time PCR." (PMID 33388091, 2021). "Here, we established a combination methylation assay of HOXA9, ONECUT2, PCDH17, PENK, TWIST1, VIM and ZNF154, which had displayed great prediction accuracy of bladder cancer in patients with hematuria by using urine samples." (PMID 31777606, 2019). "To analyze samples negative for BCL2 methylation, we expanded the MethyLight-based analysis by six additional promoter CpG islands previously reported to be frequently hypermethylated in bladder cancer, including CCNA1, EOMES, HOXA9, POU4F2, SALL3 and VIM2." (PMID 24732047, 2014). "In this study we performed an independent validation of EOMES, HOXA9, POU4F2, TWIST1, VIM, and ZNF154 methylation for the urinary diagnosis in bladder cancer surveillance." (PMID 23056278, 2012). "In addition, a 6-gene panel (HOXA9, EOMES, POU4F2, TWIST1, VIM, and ZNF154) was highly hypermethylated in the urine of bladder cancer patients as compared to healthy individuals." (PMID 37627900, 2023). "In conclusions, a urinary combined methylation assay of HOXA9, ONECUT2, PCDH17, PENK, TWIST1, VIM and ZNF154 displayed accurate prediction of bladder cancer in hematuria patients, which provided the guidance for the patients at early stage tumor and during the follow-up after operation." (PMID 31777606, 2019). "However, we found that MLH1 and HOXA9, but not the others of these commonly methylated genes, were significantly under-expressed in bladder cancer, which were in agreement with previous studies." (PMID 22140553, 2011).
colorectal cancer (11 papers, 2017 to 2024). A primary or metastatic malignant neoplasm that affects the colon or rectum. "Further, Cox multivariate regression analysis, after adjusting for potential confounding factors, identified TNM stage and HOXA9 as independent risk factors for the prognosis of colorectal cancer patients, emphasizing their clinical significance." (PMID 38285101, 2024). "In conclusion, low miR-140-3p expression and high HOXA9 expression were associated with poor prognosis in colorectal cancer patients." (PMID 38285101, 2024). "Notably, HOXA9 emerged as an independent risk factor for the prognosis of these patients, highlighting its potential as a prognostic biomarker in colorectal cancer management." (PMID 38285101, 2024). "Notably, HOXA9 emerged as an independent risk factor for colorectal cancer patients." (PMID 38285101, 2024). "This study aims to investigate the expression patterns and clinical significance of miR-140-3p and homeobox A9 (HOXA9) in colorectal cancer (CRC) selected by bioinformatic study, while elucidating their potential interplay." (PMID 38285101, 2024). "The relationship between miR-140-3p and HOXA9 expression in colorectal cancer tissues and the clinicopathological characteristics of patients was analyzed." (PMID 38285101, 2024). "Immunohistochemical staining was performed to examine the protein expression of HOXA9 in colorectal cancer and paired normal tissues." (PMID 38285101, 2024). "The Kaplan–Meier survival curves were generated by our cohort to assess the effect of miR-140-3p and HOXA9 expression on the prognosis of colorectal cancer patients." (PMID 38285101, 2024). "The high expression rate of HOXA9 protein was observed in colorectal cancer tissues compared to adjacent normal tissues (63.33%, 133 cases vs 45.71%, 96 cases)." (PMID 38285101, 2024). "In our study, bioinformatic analysis revealed low expression of miR-140-3p and high expression of HOXA9 in colorectal cancer tissues." (PMID 38285101, 2024). "In summary, the dysregulation of the miR-140-3p and HOXA9 axis in colorectal cancer is closely correlated with lymph node metastasis." (PMID 38285101, 2024). "In this study, we have identified a significantly downregulated miRNA, miR-140-3p, in colorectal cancer, and have discovered HOXA9 as a novel target of miR-140-3p." (PMID 38285101, 2024). "Taken together, our findings suggest that circ_0052184 promotes colorectal cancer progression by targeting the miR-604/HOXA9 axis." (PMID 36065412, 2022). "In this study, we found that circ_0052184 promoted colorectal cancer development by regulating the miR-604/HOXA9 axis." (PMID 36065412, 2022). "The existence of the circ_0052184/miR-604/HOXA9 regulatory network in colorectal cancer was validated." (PMID 36065412, 2022). "In conclusion, there was a circ_0052184/miR-604/HOXA9 axis in colorectal cancer, which regulated the occurrence and development of colorectal cancer." (PMID 36065412, 2022). "circ_0052184 promoted the occurrence and development of colorectal cancer by targeting the miR-604/HOXA9 axis." (PMID 36065412, 2022). "There are some reports indicating that HOXA9 knockdown can significantly decrease colony formation, invasion, and migration in colorectal cancer cells." (PMID 31043660, 2019). "In addition, the expression of HOXA9 was also increased in colorectal cancers and nasopharyngeal carcinoma than control tissues." (PMID 39462379, 2024). "Cox univariate regression analysis demonstrated that, in addition to the known prognostic factors such as differentiation, TNM stage, and lymph node metastasis, miR-140-3p and HOXA9 expression levels also significantly influenced the prognosis of colorectal cancer patients." (PMID 38285101, 2024). "Similarly, based on immunohistochemical results for HOXA9, 210 colorectal cancer patients were divided into the low HOXA9 expression group (77 cases) and the high expression group (133 cases)." (PMID 38285101, 2024).
colorectal cancer (continued). "Furthermore, we investigated the relationship between miR-140-3p or HOXA9 expression and the clinicopathological characteristics of colorectal cancer patients." (PMID 38285101, 2024). "Our study revealed that the molecular mechanism of circ_0052184 regulated the miR-604/HOXA9 axis, which might promote the malignant progression of colorectal cancer cells." (PMID 36065412, 2022). "Our goal is to ascertain how retinoic acid (RA) signaling and the regulation of HOXA9 expression might play a role in the SC origin of human colorectal cancer (CRC)." (PMID 35743243, 2022). "However, suppressing CTCF in human colorectal cancer cell line HCT116 notably reduced HOXA7 and HOXA9 expression, consistent with the finding in MLLr AML cell line MOLM13." (PMID 33001025, 2020).
chronic myeloid leukemia (10 papers, 2013 to 2023). "A low level of expression of miR-196b can cause up-regulation of BCR-ABL1 and HOXA9 expression, which leads to the development of chronic myeloid leukemia." (PMID 23894305, 2013).
colon carcinoma (10 papers, 2011 to 2025). "In conclusion, hsa_circ_0079662, as a ceRNA binding with hsa‐mir‐324‐5p, can regulate target gene HOXA9 and induced the mechanism of chemotherapy drug oxaliplatin resistance in CRC through the TNF‐α pathway in human colon cancer." (PMID 32243061, 2020). "In colon cancer (CRC), HOXA9 expression is elevated in CRC tissues compared to the normal epithelium, HOXA9 might drive CRC development and growth through regulating stem cell (SC) function." (PMID 36376832, 2022). "To further validate the relationship between miR-140-3p and HOXA9, we analyzed their correlation, and the ENCORI data revealed a negative correlation in colon cancer tissues." (PMID 38285101, 2024).
lung adenocarcinoma (10 papers, 2017 to 2025). A carcinoma that arises from the lung and is characterized by the presence of malignant glandular epithelial cells. "This study aimed to investigate methylated Homeobox A9 (meth-HOXA9) as an approach to detect ctDNA in advanced lung adenocarcinoma and compare it with mutated Kirsten rat sarcoma viral oncogene homolog (mut-KRAS) in order to determine the mutual agreement." (PMID 33322500, 2020). "Researchers have demonstrated that HOXA9 promoter methylation is responsible for its aberrant expression in lung adenocarcinoma (LUAD), non-small cell lung cancer (NSCLC), high-grade noninvasive bladder cancer, and HNSC." (PMID 38904676, 2024). "We detected meth-HOXA9 with a sensitivity of 75.0% and a specificity of 98.0% in plasma from patients with advanced lung adenocarcinoma." (PMID 33322500, 2020). "We found a good correlation between methylated HOXA9 and mutated KRAS in plasma from patients with lung adenocarcinoma." (PMID 33322500, 2020). "The median meth-HOXA9 level was 0% (range of 0–0.53%, n = 100) in donors and 0.7% (range of 0–46.6%, n = 48, p < 0.001) in lung adenocarcinoma patients." (PMID 33322500, 2020). "In this retrospective analysis of lung tissue and plasma, we found that meth-HOXA9 had high sensitivity and specificity for diagnosing advanced lung adenocarcinoma." (PMID 33322500, 2020). "The aim of the present study was to investigate methylated HOXA9 as an approach to detect ctDNA in advanced lung adenocarcinoma." (PMID 33322500, 2020). "Non-malignant lung tissue had a median of 0.4% meth-HOXA9 (range of 0.2–0.7%, n = 20), while lung adenocarcinoma tissue had a median of 13.9% meth-HOXA9 (range of 0.8–75%, n = 48, p < 0.001)." (PMID 33322500, 2020). "The present study finds that meth-HOXA9 is a sensitive and specific biomarker of advanced lung adenocarcinoma in tumor tissue, and it has promising qualities for use in liquid biopsies." (PMID 33322500, 2020). "This suggests that meth-HOXA9 may be found more commonly in advanced lung adenocarcinomas than mut-KRAS." (PMID 33322500, 2020). "Combined with HOXA9 and SEPTIN9, the detection rates in lung adenocarcinoma (LUAC) were greatly improved from 79.7% to 87.0%." (PMID 36176402, 2022). "Meth-HOXA9 and mut-KRAS were measured by ddPCR in DNA from tumor and plasma from 34 patients with incurable lung adenocarcinoma." (PMID 33322500, 2020). "The results demonstrated a high agreement between meth-HOXA9 and mut-KRAS in patients with advanced lung adenocarcinoma." (PMID 33322500, 2020). "Accordingly, we found five genes (HOXA9, TAL1, ATP8A2, ENG and SPARCL1) corresponding to the five CpG sites had above 90% hypermethylation frequencies in the 539 lung adenocarcinoma samples from TCGA." (PMID 28178989, 2017). "This contrasts with the more recent findings of Vicente at al., that the hypermethylation of HOXA9 is not an independent prognostic biomarker of cancer-specific survival among patients with lung adenocarcinoma." (PMID 40699796, 2025). "The resulting 245 differentially methylated regions were enriched for lung adenocarcinoma-specific 5-mC patterns in TCGA data and indicated transcriptional repression of several genes described to be silenced in NSCLC (e.g., PCDH10, TBX2, CDO1, and HOXA9)." (PMID 36461127, 2022). "Meth-HOXA9 is present in tissue from incurable lung adenocarcinoma but not in non-malignant lung tissue." (PMID 33322500, 2020). "In conclusion, meth-HOXA9 is present in tissue from incurable lung adenocarcinoma but not in non-malignant lung tissue." (PMID 33322500, 2020). "Gene expression analysis revealed that four of the five genes, HOXA9, TAL1, ATP8A2, ENG and SPARCL1, each harboring one of the five frequently hypermethylated CpG sites within its promoters, were also frequently down-regulated in lung adenocarcinoma." (PMID 28178989, 2017).
acute lymphoblastic leukemia (9 papers, 2010 to 2024). Leukemia with an acute onset, characterized by the presence of lymphoblasts in the bone marrow and the peripheral blood. "The simulations results seem compatible with the data available in literature; they highlight the importance of MLL, the HOXA cluster (HOXA9), and both miR-196b and miR-1976, as presented by Schotte at al. regarding Acute Lymphoblastic Leukemia (ALL)." (PMID 25080304, 2014). "HOXA9 is linked to impaired differentiation of hematopoietic precursor cells and is frequently activated in mixed-lineage leukemia (MLL)-related AML and ALL, T-cell acute lymphoblastic leukemia (T-ALL) and in Nup98-rearranged AML." (PMID 28471392, 2017). "Another group of T-cell acute lymphoblastic leukemia (T-ALL)-associated oncogenes are homeobox genes and includes members of the NK-like family, TLX1/HOX11, TLX3/HOX11L2 and NKX2-5/CSX, and of the clustered homeobox genes, HOXA5, HOXA9, HOXA10 and HOXA11." (PMID 20565746, 2010). "Other rearrangement partners of HOXA9 have been reported in lymphoid malignancies, such as TRB in T cell acute lymphoblastic leukemia (T-ALL) patients and MED12 in a pediatric patient with B cell acute lymphoblastic leukemia (B-ALL)." (PMID 34367969, 2021).